NGF (nerve growth factor)
Diseases named in the same sentence as NGF in open-access papers (continued):
Sharing a sentence is not in itself a finding about the gene and the disease.
Alzheimer disease (continued). "Numerous papers have proposed NGF as a possible therapeutic option in the treatment of Alzheimer’s disease (AD) due to its ability to sustain cholinergic activity and its neuroprotective function, together with its ability to directly inhibit amyloidogenesis." (PMID 33321704, 2020). "More recently, it has been shown that NPY was involved in Alzheimer's disease (AD) and NPY exerted neuroprotective action associated with changes in intracellular production of NGF." (PMID 33312521, 2020). "BHLHB9 can regulate the survival and differentiation of NGF-dependent neurons, and its expression level is decreased in the brains of Alzheimer's disease (AD) patients." (PMID 33192735, 2020). "ProNGF, the nerve growth factor precursor protein expression level, is increased in Alzheimer’s disease brain and cerebrospinal fluid." (PMID 31430874, 2019). "An increasing number of studies support the notion that NGF and TrkA are promising targets for new therapeutics for the treatment of Alzheimer's disease (Allen, Watson, & Dawbarn, 2011; Cattaneo & Calissano, 2012; Iulita & Cuello, 2015; Xu, Wang, & Jin, 2016)." (PMID 31301255, 2019). "Increased understanding of NGF signalling is highly important for the development of a future neurotrophic therapy of Alzheimer's disease and other neurodegenerative disorders." (PMID 31301255, 2019). "Nerve growth factor (NGF) was studied therapeutically to activate TrkA in models of Alzheimer disease (AD), and ageing, or Down syndrome, models with cholinergic deficits and memory impairment." (PMID 31244606, 2019). "Of the few, are synthetic dimeric dipeptide mimetics (loop 4 of NGF) which augment neuronal survival in models of Alzheimer's disease, Parkinson's disease, hemorrhagic stroke, and global cerebral ischemia." (PMID 29955238, 2018). "Having established that NGF modulates microglial activity in physiological conditions, we then assessed the effect of NGF on microglia in a pathology‐related context, such as Alzheimer's disease." (PMID 29473218, 2018). "Synthetic peptides that can act as NGF receptor agonists (NGF mimetics) are known to attenuate neurodegenerative pathologies in experimental models of Alzheimer's disease and Parkinson's disease; however, the existence of plant-based NGF mimetics is uncertain." (PMID 29955238, 2018). "Suggesting Mapt expression is increased in response to nerve growth factor, most of researches on Mapt are mainly referred to Parkinson disease or Alzheimer's disease." (PMID 29234374, 2017). "Neverthless, the main culprit in Alzheimer’s disease is the precursor form of NGF, pro-NGF that binds to a sortilin-p75NTR complex and activates cell death through the stimulation of Jun N-terminal kinase." (PMID 28068360, 2017). "ProNGF, the precursor of mature Nerve Growth Factor (NGF), is the most abundant NGF form in the brain and increases markedly in the cortex in Alzheimer's Disease (AD), relative to mature NGF." (PMID 28232789, 2017). "Many diseases of nervous system are related to NGF insufficiency, especially some neurodegenerative diseases, for example, depression and Alzheimer's disease." (PMID 27446228, 2016). "NGF is a pleiotropic factor for cholinergic neurons of the basal forebrain, the main target of Alzheimer's disease (AD) pathology." (PMID 27076121, 2016). "Targeted delivery of nerve growth factor (NGF) has emerged as a potential therapy for Alzheimer’s disease (AD) due to its regenerative effects on basal forebrain cholinergic neurons." (PMID 27389402, 2016). "Trials with nerve growth factor (NGF) for Alzheimer's disease had gained some degree of success but the high molecular weight of NGF reduces its ability to cross the blood-brain barrier." (PMID 26565787, 2015). "Nerve Growth Factor (NGF) holds a great therapeutic promise for Alzheimer's disease, diabetic neuropathies, ophthalmic diseases, dermatological ulcers." (PMID 26371475, 2015).
Alzheimer disease (continued). "Intracerebroventricular (ICV) administration of NGF has been proposed for several decades as a treatment for Alzheimer’s disease (AD) and clinical trials with NGF delivered by ICV administration have been performed." (PMID 30473908, 2014). "In particular, NGF is essential for cognitive function, and disrupted signaling through NGF is related to the development of Alzheimer’s disease and other neurodegenerative disorders." (PMID 24667984, 2014). "Clinical studies with chronic NGF administration in patients with Alzheimer's disease normalized electroencephalograph patterns and improved performance in words recognition tests." (PMID 25250333, 2014). "It was proposed that the relative proNGF/NGF ratio is important for their biological outcomes, especially in pathological conditions, since proNGF, the principal form of NGF in Central Nervous System (CNS), is increased in Alzheimer’s disease brains." (PMID 24713110, 2014). "Although NGF has the potential to be effective in the treatment of neurodegenerative diseases, for example, Alzheimer's disease or glaucoma, glial proliferation within the PNS has to be considered as a potential adverse effect." (PMID 24738070, 2014). "Alzheimer's disease (AD) is pathologically characterized by deposition of β-amyloid (Aβ) peptides, which closely correlates with the balance of nerve growth factor (NGF)-related TrkA/p75NTR signaling." (PMID 24356899, 2014). "In clinical trials, GDNF has been used in the treatment of Parkinson's disease, BDNF in the treatment of ALS, and NGF as a therapeutic agent in Alzheimer's disease." (PMID 24391835, 2013). "NGF has been used as a therapeutic agent for Alzheimer’s disease, peripheral neuropathies, amyotrophic lateral sclerosis and human corneal and skin ulcers." (PMID 24223654, 2013). "Increased serum NGF levels have also been found in several medical and psychiatric disorders, such as asthma, allergy, Alzheimer disease, cerebrovascular accident, and physical stress." (PMID 24098552, 2013). "Since BFC neurons are highly affected in Alzheimer’s disease (AD), NGF has been indicated as a potential protective and/or curative factor for neurodegenerative disorders associated with these neurons." (PMID 23190582, 2012). "A study of cortical neurons of cultured rats has shown that testosterone increases NGF (nerve growth factor) and p-75 nerve growth factor receptor and decreases β amyloid peptide in mouse model of Alzheimer's disease." (PMID 23056992, 2012). "Significantly, TGFβ1 signalling counteracts the inhibitory effect of Aβ on NGF signalling, possibly supplementing the attenuated activity of NGF in Alzheimer's disease and representing a potential target for the development of anti-amyloid therapies." (PMID 22849569, 2012). "For example, neurodegenerative phenotypes similar to Alzheimer’s disease (AD) are observed in a mouse model in which half of the NGF level is neutralized by antibodies." (PMID 23210531, 2012). "Nerve Growth Factor (NGF) is being considered as a therapeutic candidate for Alzheimer's disease (AD) treatment but the clinical application is hindered by its potent pro-nociceptive activity." (PMID 22666365, 2012). "The neurotrophins NGF and BDNF are associated with the early changes seen in MCI leading on to Alzheimer’s disease." (PMID 22654716, 2011). "Hypoxia also increases the replication of herpes simplex: transient cerebral ischaemia also lowers NGF levels, and these effects are relevant to the cerebral hypoperfusion seen in ageing and in Alzheimer's disease." (PMID 22254144, 2011). "Two neurotrophic factor candidates for such a pivotal role in the progression of Alzheimer’s disease are NGF and BDNF." (PMID 22654716, 2011). "Studies on the importance of the neurotrophins in Alzheimer’s disease pathology focus mainly on NGF and BDNF and their effect on neurons of the hippocampus and the ChBF." (PMID 22654716, 2011).
Alzheimer disease (continued). "These pathways referred mainly to (i) neurodegeneration (e.g. Huntington's disease, Alzheimer's disease or Parkinson's disease) and (ii) defects in synapsis (e.g. Axon guidance, NGF signaling)." (PMID 21569303, 2011). "It has been found that elevated pro-NGF levels lead to neurodegeneration in Alzheimer’s disease." (PMID 40003962, 2025). "Examples include studies investigating the neuroprotective effects of encapsulated cells delivering glial cell line-derived neurotrophic factor (GDNF) to the brain, l-dopa-secreting cells for Parkinson’s disease, and Nerve Growth Factor (NGF) for Alzheimer’s disease." (PMID 40547419, 2025). "The cognitive aspect of AD is believed to be correlated with the decline of ChAT (choline acetyltransferase) activity, and theory was tested by injecting BMSCs (bone marrow stem cells) and NGF-BMSCs (gene-modified bone marrow stem cells) into the hippocampus of a rat model with Alzheimer’s disease." (PMID 39941562, 2025). "Abnormal NGF expression and secretion are detected in the body fluids of patients with neurological and psychological disorders, such as viral encephalitis, neurogenic bladder disease, schizophrenia, and Alzheimer’s disease." (PMID 40783715, 2025). "NGF and related neurotrophic factors hold therapeutic potential for various neurological disorders, such as Alzheimer's Disease, Parkinson's Disease, Huntington's Disease, amyotrophic lateral sclerosis, spinal cord injuries, neuropathies, traumatic brain injuries, and stroke." (PMID 40153582, 2024). "The authors speculate that MMP-9 is involved in the pathophysiology of Alzheimer’s disease at an early stage, potentially through a reduction in mature nerve growth factor." (PMID 38431757, 2024). "Studies have investigated the potential of nerve growth factor (NGF), a protein that could potentially restore and protect neuron functions in Alzheimer's disease." (PMID 39156766, 2024). "The intra-brain administration of NGF was shown to have beneficial effects in patients affected by Parkinson’s and Alzheimer’s diseases (A), while the intraocular injection of NGF in an animal model of the optic nerve section was shown to prevent retinal ganglion cell degeneration." (PMID 37628852, 2023). "Thus, interfering with the NGF/proNGF balance can lead to neurodegeneration, suggesting a vicious cycle linking NGF dysmetabolism and Alzheimer’s disease." (PMID 37143894, 2023). "The NGF metabolic pathway is impaired in Alzheimer’s disease and other amyloid pathologies." (PMID 37509436, 2023). "Lately, NGF has been found to have a link to human diseases, including Alzheimer’s disease." (PMID 38276526, 2023). "Besides, as a neurotrophic drug, the targeting effect of NGF in brain in degenerative neurological diseases such as Alzheimer's disease and Parkinson's disease is significantly impeded by the presence of the blood brain barrier." (PMID 38049878, 2023). "Currently, it is believed that dysfunctions in extracellular NGF metabolism may lead to accelerated degradation of mature NGF in Alzheimer’s disease." (PMID 37958943, 2023). "We have recently demonstrated the feasibility, tolerability, and clinical efficacy of a technological platform, termed encapsulated cell biodelivery (ECB), in delivering the neurotrophin—nerve growth factor (NGF) to the brain of individuals with Alzheimer’s disease (AD)." (PMID 37596686, 2023). "Several studies have suggested that NGF and its receptors, TrkA and p75NTR, may be involved in the pathogenesis of Alzheimer’s disease (AD)." (PMID 37808473, 2023). "The role of this NGF/TrkA complex in BFCNs has been controversial in Alzheimer’s disease (AD)." (PMID 37808473, 2023). "We will also describe the main experimental facts related to the effective intranasal delivery of a mutant form of NGF [painless NGF, human nerve growth factor painless (hNGFp)] in mouse models of Alzheimer’s disease and compare it to other ways to deliver NGF to the brain." (PMID 35360160, 2022).
Alzheimer disease (continued). "When basal brain cholinergic neurons are developed in the absence of NGF, they can atrophy, which has been associated with neurological disorders such as Alzheimer’s disease." (PMID 35628626, 2022). "The crosstalk between Pdpn and NGF may indicate a potential role of Pdpn in the pathogenesis of Alzheimer’s disease." (PMID 36176432, 2022). "This has sparked many attempts to develop effective NGF treatments for Alzheimer’s disease." (PMID 35628626, 2022). "Nerve growth factor (NGF) gene therapy has been used in clinical trials of Alzheimer’s disease." (PMID 33723225, 2021). "With emerging evidence indicating a relevant relationship between Alzheimer’s disease and periodontitis, the NGF pathway might play a role as a bridge in Alzheimer’s disease patients with periodontitis." (PMID 32411181, 2020). "Taken together, the potentiating effect of sesamin on NGF-induced neurogenesis in this finding could be used for alternative treatment in neurodegenerative diseases, including Alzheimer's disease." (PMID 32308720, 2020). "Our chemical induction method significantly upregulated various trophic factors, such as BDNF, GDNF, NGF, and NT-3, which have been reported to have therapeutic effects in neurodegenerative diseases, such as Alzheimer’s disease, Parkinson’s disease, and Amyotrophic lateral sclerosis." (PMID 33104750, 2020). "The NGF pathway was involved in the repair and protection of neurons, which might function as a therapeutic target for Alzheimer’s disease." (PMID 32411181, 2020). "Metabolic dysfunction of NGF is involved in Alzheimer’s Diseases (AD) occurrence." (PMID 30103559, 2018). "Recently, the immune modulatory role of NGF was further supported by evidence showing that, in the context of Alzheimer’s disease-related insults, NGF signaling can blunt the pro-inflammatory state of microglia and promote a neuroprotective and pro-repair microenvironment." (PMID 30515104, 2018). "In addition to the neuroprotective and neuro-restorative properties of NGF, dysregulation in NGF signaling has been positively correlated with neurodegenerative disease including Alzheimer’s disease (AD), epilepsy and cancer." (PMID 30687846, 2018). "Such a finding might be relevant, e.g., for mechanisms linking proNGF/NGF unbalance and neurodegenerative processes relevant for Alzheimer's disease." (PMID 28210618, 2017). "In addition, these MSCs can also be used to overexpress nerve growth factor (NGF) to alleviate memory deficits in Alzheimer’s disease (AD)." (PMID 26848657, 2016). "Improving both NGF and IL-6 secretion can be important during neonatal development, in control of “adult” neurogenesis in the hippocampus and neocortex and also in the pathogenesis of diseases such as Alzheimer’s disease, Parkinson’s disease, or depression." (PMID 25841889, 2015). "Trials with NGF for Alzheimer's disease had gained some degree of success, but the high molecular weight of the NGF protein seems to suggest that it could not cross the blood-brain barrier." (PMID 25121118, 2014). "These researchers proposed that NGF or compounds that induce the expression of endogenous NGF may be useful in the treatment of Alzheimer's disease or other neurodegenerative diseases." (PMID 25250333, 2014). "In the central nervous system, NGF is a key neurotrophin and its dysregulation could be involved in various neuronal degeneration diseases such as Alzheimer's disease and multiple sclerosis." (PMID 25250333, 2014). "However, clinical trials with encapsulated cell biodelivery (ECB) implants for targeted delivery of NGF have given strong promise in restorative neurosurgery of patients with Alzheimer’s disease." (PMID 24300402, 2013). "A neurotrophic factor starvation, including NGF and BDNF deficiency, that begins in the early stages of Alzheimer disease (AD) and ultimately causes neuronal degeneration, cell death, and loss of cholinergic neurotransmission in the late stages of the disease has been reported." (PMID 23320097, 2013).
Alzheimer disease (continued). "Thus, GK-2, an original dipeptidemimetic of NGF, acts on models of the Alzheimer’s disease upon systemicadministration." (PMID 24303204, 2013). "Although we did not explore this possibility, this could have direct translational implications in the search for treatments of disease states affecting basal forebrain cholinergic neurons with dysfunction of NGF and its receptors, such as Alzheimer's disease." (PMID 21695154, 2011). "In 2008 following examination by autopsy of four people from the trial, Tuszynski noted that each subject exhibited a clear increase in cholinergic cell growth in response to NGF, and concluded that “additional clinical trials of NGF for Alzheimer’s disease are warranted”." (PMID 22654716, 2011). "These autoantibodies, as well as those to nerve growth factor and tau, also observed in Alzheimer's disease, may well be antibodies to pathogens, due to homology between human autoantigens and pathogen proteins." (PMID 22254144, 2011). "Also, nerve growth factor (NGF) showed the ability to reduce neuronal degeneration in animal models of Alzheimer's disease." (PMID 21349151, 2011). "More recently, however, proNGF was found to be the predominant form of NGF in brain, to be produced at increased levels in Alzheimer's disease and to induce p75NTR dependent apoptosis in cultured neurons, all properties well distinct from those of the mature NGF." (PMID 21818348, 2011). "The decline of brain DHEA and NGF levels during aging and in Alzheimer's disease might exacerbate this phenomenon, rendering neurons more vulnerable to glucocorticoid toxicity." (PMID 21541365, 2011). "An increase in MMP9, perhaps due to the increased NO levels seen in Alzheimer’s disease, may then give rise to an increase in the degradation of NGF." (PMID 22654716, 2011). "For example, the loss of supportive NGF signaling in the basal forebrain remains a favored hypothesis for the early and severe regional degeneration of cholinergic cells in Alzheimer’s disease, but NGF alone may be insufficient to explain the degeneration observed in forebrain-innervated regions." (PMID 37626771, 2023). "Moreover, ex vivo NGF-gene delivery therapy development for Alzheimer’s disease has been reported." (PMID 38276526, 2023). "The study’s results reveal a novel idea for treating Alzheimer’s disease and other neurological illnesses by employing thermoresponsive and biodegradable linear–dendritic nanoparticles for the thermally targeted and sustained release of NGF and other protein therapeutics." (PMID 36365243, 2022). "Moreover, the deprivation in NGF determines Aβ aggregation and tau hyperphosphorylation in Alzheimer’s disease (AD) while NGF addition protects against cell death and toxicity triggered by Aβ but the underlying mechanism remains unclear." (PMID 34064906, 2021). "IN-NGF has been extensively studied in preclinical models of AD, using NGF brain-deprived mice (AD11 mice), or multiple-transgenic models, co-expressing mutated forms of APP and presenilin 1 (APPxPS1) or comprising five familial Alzheimer’s disease mutations (5xFAD)." (PMID 34867367, 2021). "Thus, plasma NGF levels may serve as an early indicator of Alzheimer’s disease and a promising drug for prolonging the fertile age and combating age-related hypogonadism." (PMID 33333870, 2020). "Thus, strong NGF induction mediated by Nrf2 and ATF4 in astrocytes may be promising for the prevention of Alzheimer’s disease, as the survival of cholinergic neurons that are specifically damaged in the early phase of Alzheimer’s disease is dependent on NGF." (PMID 30959808, 2019). "Dysfunction of nerve growth factor (NGF) and its high-affinity Tropomyosin receptor kinase A (TrkA) receptor has been suggested to contribute to the selective degeneration of basal forebrain cholinergic neurons (BFCN) associated with the progressive cognitive decline in Alzheimer's disease (AD)." (PMID 28632177, 2017).